LRPPRC (leucine rich pentatricopeptide repeat containing)
Diseases named in the same sentence as LRPPRC in open-access papers (continued):
Sharing a sentence is not in itself a finding about the gene and the disease.
ovarian carcinoma (continued). "This work brings to light, for the first time, a possible functional relationship between SDHA and LRPPRC in the development and progression of ovarian cancer disease." (PMID 40563592, 2025). "According to recent reports, LRPPRC can affect proliferation, apoptosis, stemness, and autophagy in ovarian cancer." (PMID 38643468, 2024). "LRPPRC has been reported to influence autophagy and to play a crucial role in promoting proliferation, migration, and invasion in ovarian cancer." (PMID 38643468, 2024). "In this context, our experiments showed that LRPPRC expression is increased in ovarian cancer tissues and negatively correlated with OS." (PMID 37496051, 2023). "Overall, the current study provides valuable insights into the mechanism of action of OXPHOS in ovarian cancer mediated by LRPPRC and highlights novel strategies for ovarian cancer therapy." (PMID 37496051, 2023). "GAA inhibits cell proliferation and affects OXPHOS in OC cells through the degradation of the LRPPRC protein, supporting its potential utility as a natural therapeutic agent for ovarian cancer." (PMID 37496051, 2023). "To determine the correlations between LRPPRC and ovarian cancer, we compared its protein expression level in advanced serous OC ( n = 317) and benign ovarian cysts (n = 79) by IHC." (PMID 37496051, 2023). "GAA inhibits OC progression by suppressing OXPHOS complex synthesis via targeting LRPPRC protein, supporting its potential utility as a natural therapeutic agent for ovarian cancer." (PMID 37496051, 2023). "We additionally analyzed the correlation between LRPPRC expression and overall survival (OS) of 107 patients with ovarian cancer from previously generated microarray data sets." (PMID 37496051, 2023). "The decrease of LRPPRC expression in ovarian cancer cells was further confirmed by immunoblotting, in which GAA caused a concentration-dependent decrease of LRPPRC protein in both A2780 and SKOV3 cell lines." (PMID 37496051, 2023). "Therefore, we analyzed GeoMx spatial transcriptomics data to determine the SDHA and LRPPRC expression patterns in human HGSOC samples to provide insight into their potential roles in driving ovarian cancer onset and disease progression." (PMID 40563592, 2025). "Targeting LRPPRC in the context of oxidative phosphorylation may inhibit the progression of ovarian cancer." (PMID 41516324, 2025). "Collectively, our in vivo data demonstrated that shikonin treatment results in a durable therapeutic response and can be an effective treatment in preselected SDHA- and LRPPRC-overexpressing ovarian tumors, which introduces hope for improving current therapies for ovarian cancer patients." (PMID 40563592, 2025). "Importantly, our in vivo findings demonstrated that inhibition of LRPPRC function by shikonin results in a sustained therapeutic benefit, as evidenced by a two-fold extension of median survival in mouse models of ovarian cancer." (PMID 40563592, 2025). "Recent studies have found that LRPPRC is highly expressed in ovarian cancer tissues." (PMID 41516324, 2025). "Due to KEGG analysis results showing that the interacting proteins of HAPSTR1 are associated with the ubiquitin-mediated proteolysis pathway, we searched for enzymes reported to play a role in ovarian cancer and are related to LRPPRC and the ubiquitin-proteasome pathway in our IP-MS results." (PMID 38643468, 2024). "Dysfunction of LRPPRC and MAP1S is associated with poor survival of ovarian cancer patients." (PMID 24722279, 2014). "Additionally, we compared LRPPRC expression levels in ovarian cancer cell lines." (PMID 41516324, 2025). "In summary, we investigated the unique metabolic features of ovarian cancer and discovered that tumors with a high-OXPHOS phenotype are characterized by the concomitant overexpression of SDHA and LRPPRC." (PMID 40563592, 2025).
ovarian carcinoma (continued). "Knockdown of LRPPRC led to decreased levels of OXPHOS and tumorigenicity in OC cells, supporting the utility of LRPPRC suppression as a novel strategy for ovarian cancer management." (PMID 37496051, 2023). "We aimed to determine changes in SDHA and LRPPRC gene expression ranging from early precursor lesions to advanced-stage HGSOC to provide insight into the potential role of those molecules in the development and progression of ovarian cancer disease." (PMID 40563592, 2025). "We examined the unique metabolism of ovarian cancer overexpressing succinate dehydrogenase subunit A (SDHA) and identified a distinctive vulnerability of these tumors to agents targeting key regulators of the OXPHOS pathway, particularly the LRPPRC protein." (PMID 40563592, 2025). "The possible reason could be the basal expression levels of LRPPRC and SCO1 differ between the ovarian cancer cell lines A2780 and SKOV3, with SKOV3 exhibiting lower expression levels." (PMID 41516324, 2025). "Our novel findings shed light on an unexplored link between SDHA and LRPPRC in ovarian cancer, and to the best of our knowledge, there are no studies directly investigating a functional relationship between those key metabolic regulators." (PMID 40563592, 2025). "We next evaluated SDHA and LRPPRC gene and protein expression patterns in precursor lesions and advanced HGSOC samples and demonstrated that the tumor-specific upregulation of SDHA consistently coincides with LRPPRC overexpression, especially in advanced ovarian cancer." (PMID 40563592, 2025). "Furthermore, it was found that inhibiting LRPPRC expression not only diminishes the translation of the core subunit MTCO1 of complex IV and the copper chaperone molecule SCO1 in A2780 and SKOV3 ovarian cancer cells, but also reduces the expression levels of FDX1 and LIAS." (PMID 41516324, 2025). "No studies have yet reported the relationship between LRPPRC and cuproptosis, or its key molecule FDX1, in ovarian cancer." (PMID 41516324, 2025).
prostate carcinoma (7 papers, 2015 to 2025). A carcinoma that arises from epithelial cells of the prostate gland. "For instance, IGF2BP1 enhances mRNA stability and has been demonstrated to combine with circPTPRA in the cytoplasm of bladder cancer cells; additionally, the upregulation of LRPPRC is closely related to prognosis, survival and resistance in prostate cancer." (PMID 39779466, 2025). "LRPPRC (leucine rich pentatricopeptide repeat containing) is considered as a negative regulator of autophagy and demonstrates upregulation in prostate cancer tissues." (PMID 35317831, 2022). "As an autophagy inhibitor, upregulation of LRPPRC reveals poor prognosis, low overall survival, and resistance to hormone therapy of prostate cancer." (PMID 35317831, 2022). "An analysis has shown that LRPPRC is overexpressed in 75% of prostate cancer patients, while it has low expression in 10% of prostate cancer patients." (PMID 35317831, 2022). "(2014) reported that LRPPRC played a critical role in the development of prostate cancer and that its inhibition could present a potential molecular approach for the treatment of prostate cancer." (PMID 28188704, 2017).
viral infections (7 papers, 2012 to 2024). "LRPPRC, a regulator of mRNA encoded by mitochondrial DNA, plays a significant role in viral infections by inhibiting antiviral signaling mediated by the mitochondrial antiviral-signaling protein (MAVS), acting as a suppressor in hepatitis C virus infection." (PMID 39622968, 2024). "LRPPRC dysregulation is associated with the occurrence of various diseases, including viral infections and tumors." (PMID 38436011, 2024). "Co-immunoprecipitation RT-PCR experiments confirmed that LRPPRC associated with HIV-1 nucleic acids during the early steps of virus infection." (PMID 22808186, 2012). "Most studies have found that LRPPRC is closely associated with neurodegenerative diseases, neurofibromatosis, venous thromboembolism, non-alcoholic fatty liver, and viral infections and that its dysregulation may initiate carcinogenesis and inhibit cancer cell apoptosis." (PMID 37139237, 2023). "Recently, growing evidence has pointed out that LRPPRC dysregulation is related to various diseases ranging from tumors to viral infections." (PMID 31178748, 2019). "Further investigating these new functions of LRPPRC should provide novel opportunities for a better understanding of its pathological role in diseases from tumors to viral infections and as a potential biomarker and molecular target for disease treatment." (PMID 31178748, 2019). "In addition, LRPPRC plays a potential role in Parkinson's disease, neurofibromatosis 1, viral infections, and venous thromboembolism." (PMID 31178748, 2019). "For example, HCV NS5A localizes to the endoplasmic reticulum during viral infection, while the NS5A binds to LRPPRC on mitochondria to inhibit the MAVS-regulated antiviral signaling during HCV infection." (PMID 31937766, 2020).
bladder cancer (6 papers, 2021 to 2025). "METTL14, YTHDC1, and WTAP may be protective factors for bladder cancer, the higher expressions were related to the longer overall survival of patients, while IGF2BP1-3, YTHDF1, LRPPRC, ALKBH5, and FTO were risk factors for bladder cancer." (PMID 37701836, 2023). "Likewise, COPA and LRPPRC were colocalized in the cytoplasm of bladder cancer cells." (PMID 40112217, 2025). "Recently, Chen and colleagues reported that lncRNA DANCR directly interacted with LRPPRC and guided LRPPRC protein to bind and stabilize the mRNAs of CCND1, PLAU, and IL-11, resulting in enhanced proliferation, migration, and invasion of bladder cancer cells." (PMID 34671012, 2021).
glioma (5 papers, 2022 to 2025). A benign or malignant brain and spinal cord tumor that arises from glial cells (astrocytes, oligodendrocytes, ependymal cells). "The TCGA glioma dataset was used to construct the risk model, and the risk score was calculated using the following formula: risk score = (− 0.3358 × LRPPRC expression) + (1.4536 × RPN1 expression) + (0.5002 × GYS1 expression)." (PMID 37864127, 2023). "Additionally, a study revealed that high expression of LRPPRC was positively correlated with a favorable prognosis for gliomas, but increased expression of RPN1 and GYS1 was associated with an unfavorable prognosis." (PMID 40109666, 2025). "GYS1, NDUFA11, OXSM, RPN1, and SLC3A2 play a role in promoting cancer in glioma, while LRPPRC, NCKAP1, NDUFS1, NUBPL and SLC7A11 play a role in inhibiting tumour." (PMID 39993959, 2025). "Recently, the disulfidptosis related genes (DRGs) SLC3A2, NDUFA11, OXSM, NUBPL, LRPPRC, RPN1, and GYS1 were found to be significantly associated with glioma cells." (PMID 40109666, 2025). "We explored their expression in dataset from TCGA and found that LRPPRC was downregulated, while RPN1 and GYS1 were upregulated in TCGA glioma dataset." (PMID 37864127, 2023).
pancreatic cancer (5 papers, 2021 to 2025). "The Compared with adjacent non-tumorous tissues, we found a higher level of EIF3H, IGF2BP2, IGF2BP3, KIAA1429 in all six pancreatic tumor tissues, LRPPRC was overexpressed in five pancreatic tumor tissues, while the expression of METTL3 decreased in four pancreatic tumor tissues." (PMID 34332578, 2021). "Likewise, LRPPRC promoted cell proliferation, metastasis, and invasion of pancreatic cancer cells." (PMID 40775462, 2025). "Further, LRPPRC was a multifunctional protein involved in energy metabolism, and we found high LRPPRC enriched in pancreatic cancer, and it may play an essential role in pancreatic tumorigenesis by connecting an oncogenic gene expression with energy production." (PMID 34332578, 2021). "An m6Ascore based on the expression of IGF2BP2, IGF2BP3, KIAA1429, METTL3, EIF3H and LRPPRC is proposed as an indicator of TME status and is instrumental in predicting the prognosis of pancreatic cancer patients." (PMID 34332578, 2021). "In the oncomine database, expression of KIAA1429, LRPPRC, IGF2BP2, IGF2BP3, and EIF3H was higher in pancreatic cancer than normal tissues." (PMID 34332578, 2021).
bladder urothelial carcinoma (4 papers, 2023 to 2024). "Among the signature genes, LRPPRC has been implicated in promoting the tumorigenesis of bladder urothelial carcinoma by regulating intracellular ROS homeostasis and holds important prognostic significance." (PMID 37427103, 2023). "Previous study has established that LRPPRC is often upregulated in urothelial carcinoma of the bladder, where it regulates redox balance via the circANKHD1/FOXM1 pathway to drive tumorigenesis." (PMID 39445012, 2024). "In addition, a group of disulfidptosis-related genes (GYS1, LRPPRC, NDUFA11, OXSM, RPN1, SLC3A2, and SLC7A1) are found to influence the prognosis of bladder urothelial carcinoma via immune cell infiltration." (PMID 39701955, 2024).
Obesity (4 papers, 2022 to 2025). Accumulation of substantial excess body fat. "For example, LRPPRC is involved in cytoskeletal regulation and bone development, PMAIP1 is associated with obesity, and PPP1R11 has roles in cell proliferation and fat metabolism." (PMID 40630222, 2025). "In contrast, METTL15, zinc finger CCCH-type containing 13 (ZC3H13), fat mass and obesity-associated (FTO), leucine-rich pentatricopeptide repeat containing (LRPPRC), and RNA-binding motif protein 15B (RBM15B) showed widespread CNV frequency loss." (PMID 34979500, 2022). "Our results reveal that specific loss of LRPPRC in the liver does not lead to obesity but induces deleterious remodeling of the liver matrix with signs of fibrosis and impaired hepatic structure similar in both sexes recapitulating to some extent the lean-NAFLD phenotype in humans." (PMID 38519536, 2024).
ischemic stroke (3 papers, 2022 to 2025). A stroke disorder caused by obstruction of blood flow to the brain, due to thrombotic (local blood clot formation) or embolic (due to a blood clot or other material traveling from another site) event. "In ischemic stroke, it has been found that LRPPRC is one of the key regulators of m6A and serves as an immune marker." (PMID 40555877, 2025).
lactic acidosis (3 papers, 2015 to 2025). Metabolic acidosis characterized by the accumulation of lactate in the body. "Yet, it remains unclear how this biochemical defect brings about the pathological phenotype associated with LSFC, due in part to a lack of data on the functional impact of LRPPRC gene mutation, and our limited knowledge of factors triggering fatal lactic acidosis crises." (PMID 25835550, 2015).
Parkinson disease (3 papers, 2014 to 2023). A progressive degenerative disorder of the central nervous system characterized by loss of dopamine producing neurons in the substantia nigra and the presence of Lewy bodies in the substantia nigra and locus coeruleus. "The LRPPRC gene has not yet been associated with patients with Parkinson ́s disease from the Faroe Islands and may be considered as a candidate gene in future studies." (PMID 36404349, 2023). "Since LRPPRC-Parkin interaction may play important roles in two seemingly contradicting events of uncontrolled cell growth in cancers and cell death and neuron degeneration in Parkinson's disease, manipulating the interaction provides a new opportunity to target both diseases." (PMID 24722279, 2014).
Sepsis (3 papers, 2023 to 2025). Sepsis is defined as life-threatening organ dysfunction caused by a dysregulated host response to infection. "In this predictive nomogram, the expression levels of FTO, HNRNPC, RBMX, YTHDC1, LRPPRC, and RBM15B were negatively associated with the risk score of patients with sepsis and were regarded as protective factors in sepsis." (PMID 36781867, 2023). "The six intersection disulfidptosis‐related genes including LRPPRC, SLC7A11, GLUT, MYH9, NUBPL and GYS1 exhibited higher predictive ability for sepsis with an accuracy of 99.7%." (PMID 39400961, 2024).
atherosclerosis (2 papers, 2016 to 2022). A disease characterized by the build-up of fatty material and calcium deposition in the arterial wall resulting in partial or complete occlusion of the arterial lumen. "Consequently, increased hepatic LRPPRC and OxPhos rate resulted in the reduction of serum and hepatic triglyceride and cholesterol levels, which would lower the risk of atherosclerosis and other cardiovascular diseases." (PMID 27462273, 2016).
autism (2 papers, 2012 to 2025). Persistent deficits in social interaction and communication and interaction as well as a markedly restricted repertoire of activity and interest as well as repetitive patterns of behavior. "CNTNAP2 has previously been linked to autism and intellectual disability, BRAF to epilepsy, TRANK1 to schizophrenia, and LRPPRC/MYO7A to mitochondrial and ciliary disorders." (PMID 40282380, 2025). "The expression of DNAJC19, DNM1L, LRPPRC, SLC25A12, SLC25A14, SLC25A24 and TOMM20 were consistently reduced in at least two of the brain regions of autism patients compared to controls." (PMID 23116158, 2012). "The expression of DNAJC19, DNM1L, LRPPRC, SLC25A12, SLC25A14, SLC25A24 and TOMM20 were reduced in at least two of the brain regions of autism patients." (PMID 23116158, 2012). "The expression of DNM1L and LRPPRC were reduced in the ACG and MC of autism patients." (PMID 23116158, 2012).
gastric adenocarcinoma (2 papers, 2020 to 2024). "LRPPRC was detected as upregulated in lung and gastric adenocarcinoma, leading to apoptosis resistance and invasive activity in these cancer cells via its overexpression in vitro." (PMID 38397966, 2024).
heart failure (2 papers, 2016 to 2023). Inability of the heart to pump blood at an adequate rate to meet tissue metabolic requirements. "In summary, our results provide mechanistic information about the roles of previously studied genes namely, NDUFS4, LRPPRC, and COQ7, in heart failure." (PMID 37276142, 2023).
hepatitis C (2 papers, 2020 to 2021). "As documented for hepatitis C, different viral proteins could also influence the efficacy of the immune response in LSFC patients by directly interacting with LRPPRC." (PMID 33085679, 2020).
melanoma (2 papers, 2021 to 2024). A malignant, usually aggressive tumor composed of atypical, neoplastic melanocytes. "Comparing primary melanoma and metastases, we found that ALKBH5, ELAVL1, FMR1, HNRNPA2B1, HNRNPC, IGF2BP1/2/3, KIAA1429, LRPPRC, RBM15, YTHDC1/2, YTHDF1/3, and ZC3H13 were significantly upregulated in metastases, while RBM15B and METTL3 were significantly upregulated in primary melanoma." (PMID 34993195, 2021).
periodontitis (2 papers, 2022 to 2023). An acute or chronic inflammatory process that affects the tissues that surround and support the teeth. "Additionally, LRPPRC may potentially impact the MHC molecules HLA-B and HLA-DOA in periodontitis." (PMID 37892851, 2023).
steatosis (2 papers, 2015 to 2024). Increased lipid within the cytoplasm of cells. "Taken together, these data argue that augmentation of hepatic OXPHOS by ectopic expression of LRPPRC mitigates both steatosis and inflammation in NAFLD." (PMID 25933096, 2015).
type 2 diabetes (2 papers, 2024 to 2026). "Moreover, through a large prospective cohort study, elevated plasma LRPPRC K224 lactylation (the human homolog of mouse LRPPRC K223) was identified as an independent predictor of cognitive impairment in type 2 diabetes patients." (PMID 41942754, 2026).
acute lymphoid leukemia (1 paper, 2012). "It seems that LRPPRC may be related to transactivation of MDR genes (ABCB1 and LRP) by invMED sequence in acute lymphoid leukemia." (PMID 22458888, 2012).
alcohol use disorder (1 paper, 2022). "A recent study reported that the LRPPRC gene was DMRs annotated in alcohol use disorder subjects, one of the adverse implications of prenatal METH exposure, such as polysubstance abuse." (PMID 35928279, 2022).